ABCB1 (ATP binding cassette subfamily B member 1)
Diseases named in the same sentence as ABCB1 in open-access papers (continued):
Sharing a sentence is not in itself a finding about the gene and the disease.
depression (21 papers, 2012 to 2025). "This transporter is encoded by ABCB1 gene, and genetic variations within ABCB1 gene have been proposed to affect drug efflux and have been previously associated with depression." (PMID 38791151, 2024). "In this context, we aimed to evaluate the role of C1236T, G2677TA and C3435T ABCB1 genetic polymorphisms in antidepressant treatment phenotypes from a cohort of patients harboring Major Depressive Disorder." (PMID 38791151, 2024). "In this study, we explored the influence of ABCB1 polymorphisms on depression treatment outcomes, focusing on TRD, relapse, time to remission and time to relapse." (PMID 38791151, 2024). "Through meta-analysis, this study further explored the relationship between ABCB1 gene polymorphism and the efficacy of antidepressants, so as to provide an etiological basis for individualized treatment in patients suffering from depression." (PMID 34260525, 2021). "Studies have also reported association of the ABCB1 variant rs1045642 (C3435T) with major depressive disorder in Japanese." (PMID 24586633, 2014). "The C allele of the ABCB1-rs1045642 polymorphism was connected with boosted interpersonal sensitivity among Japanese populations; this allele has been generally accepted as one of the vulnerability factors for depression." (PMID 36698099, 2023). "There are few studies on the relationship between gene polymorphism of ABCB1 and depression in the Chinese Han population; only a team of Taiwan scholars studied the relationship between the efficacy of escitalopram and gene polymorphism of ABCB1 in patients with depression." (PMID 31333472, 2019). "The relationship between genetic variants and depression severity or remission was also evidenced by findings involving SLC6A4, ABCB1, and HTR2A." (PMID 40725795, 2025). "While certain ABCB1 variants do not necessarily increase the risk of developing depression, they can still influence treatment response, depending on genetic and ethnic background." (PMID 40725164, 2025).
Obesity (20 papers, 2011 to 2026). Accumulation of substantial excess body fat. "Here, we investigated if overweight and obesity in pregnant women altered mRNA expression of ABCB1 encoding P-gp or ABCG2 encoding BCRP in first trimester human placenta." (PMID 36997557, 2023). "In the present work, analysis of the 1236C>T, 2677G>T/A, and 3435C>T polymorphisms in the ABCB1 gene have shown that 1236C>T and 2677T>A polymorphisms seem to be associated with overweight/obesity in children and adolescents with ASD treated with risperidone." (PMID 33240086, 2020). "The results demonstrated that the ABCB1 1236C>T and duration of risperidone treatment associated with overweight/obesity." (PMID 33240086, 2020). "Association between ABCB1 1236C>T, 2677G>T/A, and 3435C>T polymorphisms and overweight/obesity in children and adolescents with ASD treated with risperidone (n = 134)." (PMID 33240086, 2020). "The second aim was to investigate the association of the HTR2C -759C>T, ABCB1 1236C>T, ABCB1 2677G>T/A, and ABCB1 3435C>T polymorphisms with risperidone-induced overweight and obesity in children and adolescents with ASD." (PMID 33240086, 2020). "In a multivariate logistic regression model, ABCB1 1236C>T SNP seems to be associated with risperidone-induced overweight/obesity in children and adolescents." (PMID 33240086, 2020). "Most interestingly, a study performed in a Japanese cohort revealed that a single nucleotide polymorphism on ABCB1 gene was associated with obesity." (PMID 21949682, 2011). "However, our result demonstrated that there was a borderline significant trend of the association between ABCB1 (1236C>T) polymorphism and obesity in children and adolescents with ASD (Bonferroni corrected p-value = 0.09)." (PMID 33240086, 2020). "Moreover, considering the role of target receptor HTR2C and efflux transporter P-gp in risperidone pharmacokinetics, we hypothesized that polymorphisms in the HTR2C and ABCB1 genes might impact obesity in children and adolescents treated with risperidone." (PMID 33240086, 2020). "A recent study explored in humans that obesity increases the mRNA expression of placental ABCB1 before 12 weeks of pregnancy." (PMID 40725223, 2025). "A human study found a negative correlation between BMI values and the expression levels of ABCB1 in the brain, suggesting P-gp levels are reduced in obesity." (PMID 38678254, 2024). "Older age, hyperglycemia, and obesity or poor nutritional status, such as single-nucleotide polymorphisms (SNPs) in the FGD4, EPHA5, and FZD3 genes and ABCB1 and GSTP1 polymorphisms, have been associated with the development of taxane-related neuropathy." (PMID 33922821, 2021). "This study investigated the relation of overweight/obesity with HTR2C –759C>T, ABCB1 1236C>T, ABCB1 2677G>T/A, and ABCB1 3435C>T polymorphisms in children and adolescents with ASD treated with risperidone." (PMID 33240086, 2020). "Previous studies have suggested that the function of ABCB1 might be affected by obesity, suggesting a future direction for the exploration of ABCB1 function." (PMID 36144279, 2022). "Obesity-associated adipokines, leptin and resistin, can upregulate ABCB1 (P-glycoprotein, P-gp)." (PMID 32774439, 2020). "Based on similar roles as metabolic enzymes, we hypothesized that ABCB1 in the human liver would vary with age, sex, ethnicity, or obesity, and tested this in both the lysates as well as a larger cohort of 87 liver S9 fractions (7 days–87 years)." (PMID 28218636, 2017). "We therefore additionally evaluated liver triglyceride levels to understand if the pathological manifestation of obesity (liver fat) could alter ABCB1 expression." (PMID 28218636, 2017). "Moreover, diet restriction was shown to induce a very strong up-regulation of the ABCB1a gene (one of the two mice orthologs of the human ABCB1 gene) in mice and, more importantly, Pgp knock-out mice developed obesity, hepatic steatosis and increased liver TGs." (PMID 33557317, 2021).
Obesity (continued). "For the pharmacogenetic factors, –759C>T polymorphism of HTR2C gene and 1236C>T, 2677G>T/A, and 3435C>T polymorphisms of ABCB1 gene were not likely to be associated with the susceptibility to overweight/obesity in children and adolescents treated with risperidone." (PMID 33240086, 2020). "Frequency of ABCB1 haplotypes in children and adolescents with ASD treated with risperidone with overweight/obesity and with healthy weight (n = 134)." (PMID 33240086, 2020). "However, the relation of ABCB1 1236C>T with overweight/obesity did not survive Bonferroni correction." (PMID 33240086, 2020). "Future studies using larger samples are required to establish unequivocally whether or not ABCB1 genotypes are related to the development of obesity in children and adolescents treated with risperidone." (PMID 33240086, 2020). "Moreover, for gender analysis, ABCB1 and HTR2C genes polymorphisms were not related to overweight/obesity in both males and females." (PMID 33240086, 2020). "Neither mRNA nor protein levels varied with sex, ethnicity, obesity or triglycerides in lysates or S9 (that showed the same relationships), but protein levels were lower in pediatric S9 (p < 0.0001), with 76% of adult ABCB1 present at birth and predicted to mature in 5 years." (PMID 28218636, 2017).
colon adenocarcinoma (19 papers, 1998 to 2024). "In particular, G. biloba extract at 200 μg/mL increased by 9.5-fold human PXR activation and the expression of PXR target genes, i.e., CYP3A4, CYP3A5 and ABCB1 (encoding P-gp) in human LS180 colon adenocarcinoma cells." (PMID 32635538, 2020). "In the present work, the anticancer activity of symmetrical selenoesters was investigated by studying the reversal of efflux pump-related and apoptosis resistance in sensitive and resistant human colon adenocarcinoma cells expressing the ABCB1 protein." (PMID 36839934, 2023). "The aim of our study was to investigate the anticancer effect of symmetrical selenoesters on sensitive and resistant human colon adenocarcinoma cells expressing ABCB1 protein." (PMID 36839934, 2023). "The authors reported the antiproliferative effects of synthesized silver nanoparticles in both parental drug-sensitive (Colo 205) and ABCB1 overexpressing human colon adenocarcinoma cells (Colo 320)." (PMID 36836823, 2023). "The potent ABCB1 inhibiting ketone-selenoesters were tested regarding their apoptosis-inducing activity on MDR Colo 320 colon adenocarcinoma cells." (PMID 34572790, 2021). "The antiproliferative capacity of compounds 12–18 was tested against human colon adenocarcinoma cells (Colo 205 sensitive and the resistant Colo 320/MDR-LRP expressing ABCB1)." (PMID 39065005, 2024). "Fluphenazine also decreased the expression of MDR1 (ABCB1) and COX2 genes in doxorubicin-resistant LoVo/Dx colon adenocarcinoma cell lines." (PMID 36671340, 2023).
breast tumor (18 papers, 2008 to 2025). "The incidence of ABCB1 expression was higher in patients receiving cytotoxic chemotherapy, and its expression in breast tumours was associated with treatment failure and poor chemotherapeutic response." (PMID 33801148, 2021). "For example, hypomethylation of the ABCB1 downstream promoter region was found to be significantly associated with drug resistances in breast tumor cells due to increased expression of ABCB1 transcripts." (PMID 28422980, 2017). "Changes in ABCB1 promoter methylation, ABCB1 promoter usage and ABCB1 transcript expression can be temporally and causally correlated with the acquisition of drug resistance in breast tumor cells." (PMID 26703582, 2015). "Besides, the observations in a study involving 124 primary breast tumour specimens showed that a high level of ABCB1 expression was associated with TNBC metastatic spread." (PMID 33801148, 2021). "Researchers characterized changes in the expression level of the ABCB1 gene in a breast tumor compared to benign breast tissue surrounding the tumor." (PMID 36674773, 2023). "Previous studies by the same authors confirmed that ABCB1 mRNA activation is the main mechanism of breast tumour resistance to docetaxel in in vitro models." (PMID 35631534, 2022). "For instance, Trock and Leonessa conducted a meta-analysis of 31 studies from 1989–1996 to examine the ABCB1 expression in breast tumours and found that 41% of the breast tumour samples were positive for ABCB1 expression." (PMID 33801148, 2021). "Using PET imaging, we demonstrated that [18F]AVT-011 can measure ABCB1 function in a mouse model of drug-resistant breast tumors." (PMID 31729540, 2020). "Wild-type mice were implanted orthotopically with breast tumors comprising three levels of Abcb1a/b expression and ABCB1 protein levels found in clinical tumors: basal, intermediate (3-fold increase in Abcb1a/b), or high (~ 521-fold increase in Abcb1a/b)." (PMID 31729540, 2020). "The expression of ABCB1 in breast tumours significantly varies between individuals." (PMID 33801148, 2021). "However, since cDNA microarray studies suggest that multiple proteins play a role in acquired drug resistance, it would be unexpected that ABCB1 siRNAs could fully restore drug sensitivity in our drug-resistant breast tumour cell lines." (PMID 18980695, 2008). "To measure ABCB1 function in tumors, we performed PET experiments using both [18F]AVT-011 and [18F]FDG in mice bearing orthotopic breast tumors (n = 7–10/group) expressing clinically relevant levels of ABCB1." (PMID 31729540, 2020). "For example, in both mouse and human breast tumors, the washout rate of the SPECT radiotracer [99mTc]sestamibi was 2- to 5-fold higher in tumors with high levels of ABCB1 than in those with basal levels." (PMID 31729540, 2020). "Interestingly, the expression levels of PTGS2 (-4.80-fold change) and EGFR (-2.45-fold change) regulated by hsa-mirR128, ABCB1 (-2.21-fold change), IGF1 (-2.19-fold change), and IL6 (-2.85-fold change) regulated by hsa-miR-223, were significantly reduced in breast tumour tissue." (PMID 32577155, 2020). "Similarly in breast tumor cells, osteopontin may activate the hedgehog pathway and enhance drug resistance through GLI1-dependent regulation of ABCB1 and ABCG2." (PMID 27400751, 2016).
anemia (17 papers, 2015 to 2025). A reduction in the number of red blood cells, the amount of hemoglobin, and/or the volume of packed red blood cells. "In our study, at ABCB1 rs1045642, compared with the CC genotype, patients with the T allele had a lower risk of anemia and thrombocytopenia, which is consistent with the results of Jian Han’s study." (PMID 40832604, 2025). "In model II, patients with rivaroxaban anemia, ABCB1 rs3842 variant homozygote (CC) and APOB rs13306198 variant allele (AG, AA) had a higher risk of bleeding risk." (PMID 36145636, 2022). "Our results showed that the presence of common homozygote CC of ABCB1 polymorphism p.Ile1145= (rs1045642) increased the risk of recurrent anemia." (PMID 29507678, 2018). "Variant alleles at ABCB1 c.1236C>T have been associated with higher risk of anemia." (PMID 33326171, 2021). "Higher ALB level, female, ABCB1 rs1045642, MTHFR rs1801131, and MTHFD1 rs2236225 were associated with lower risk of anemia, while the combination of furosemide, torasemide, bumetanide, and levetiracetam associating with higher risk." (PMID 40832604, 2025). "In particular, rs1128503 (ABCB1, C > T), rs12762549 (ABCC2, C > G), rs363717 (ABCA1, A > G) and rs11615 (ERCC1, T > C) were significantly associated with grade 3–4 anemia (p = 0.035, OR 1.58; p = 0.005, OR 0.55; p = 0.001, OR 1.31 and p = 0.024, OR = 1.58)." (PMID 25881102, 2015). "Therefore, we constructed a risk scoring system using both demographic factors and genetic factors, which remained in Model II; overdose, rivaroxaban, anemia, ABCB1 rs3842, APOB rs693 and APOB rs13306198 were taken as 2, 1, 1, 1, 3 and 1 point, respectively." (PMID 36145636, 2022). "The recurrence of anemia in four or more cycles of FAC chemotherapy was connected to the presence of the rare allele G of variant p.Pro329Ala in ALDH3A1 gene (rs2228100) and common homozygote CC of another ABC transporter gene polymorphism – ABCB1 p.Ile1145= (rs1045642)." (PMID 29507678, 2018).
small cell lung carcinoma (17 papers, 1989 to 2025). Small cell lung cancer (SCLC) is a highly aggressive malignant neoplasm, accounting for 10-15% of lung cancer cases, characterized byrapid growth, and early metastasis. "We examined the effects of the histone deacetylase inhibitor trichostatin A (TSA) on ABCB1 gene expression in small cell lung carcinoma (SCLC) drug-sensitive (H69WT) or etoposide-resistant (H69VP) cells." (PMID 17667922, 2007). "Among the small cell lung cancer cell lines, in GLC-4 cells the promoters of both ABCB1 and ABCG2 were found to be higher methylated than in DMS114 cells." (PMID 27689338, 2016). "One study has found that ABCB1 and ABCG2 might mediate chemoresistance in HER2-positive small cell lung cancer cells." (PMID 34244494, 2021). "Thus, the strongly ABCC1- and LRP-overexpressing small cell lung cancer GLC4/ADR and the colchicine-selected, ABCB1-overexpressing, HeLa cell subclone KB-C-1, were equally sensitive against hellebrigenin as their parental cell lines." (PMID 23621895, 2013).
renal cell carcinoma (16 papers, 2000 to 2024). "This intrigued us, as renal cell carcinomas are often positive for expression of P-glycoprotein (P-gp, encoded by the ABCB1 gene), an ATP-binding cassette (ABC) multidrug efflux pump that confers drug resistance." (PMID 37840856, 2023). "This study aimed to evaluate the associations of ABCG2 and ABCB1 polymorphisms with sunitinib-induced toxicity and efficacy in renal cell carcinoma (RCC) by meta-analysis." (PMID 33762959, 2021). "The possible roles played by the drug efflux pumps in CSCs have also been elucidated with the drug resistance protein ABCB1 recently being implicated in the functioning of Renal Cell carcinoma SP cells." (PMID 27229859, 2016). "SYMD2 was found to promote the expression of P-glycoprotein (P-gp) also known as multidrug resistance protein 1 (MDR1) or ATP binding cassette B1 (ABCB1) in renal cell carcinoma (RCC) and CRC cells." (PMID 39703687, 2024). "Among microenvironment–cell interaction-mediated regulation of ABCB1, a family of ECM proteins called CCN (CYR61/CTGF/NOV) was demonstrated to regulate ABCB1 and to confer vinblastine resistance in renal cell carcinoma cells targeting αv β3." (PMID 33834020, 2021). "Also, ABCB1 mRNA and protein levels were found to be lowered in renal cell carcinoma tissue compared to normal looking cortex in 82 nephrectomised cancer patients." (PMID 23977225, 2013). "In this retrospective study the expression of two of these transporter efflux pumps, namely MDR-1 P-gp (ABCB1) and MRP-1 (ABCC1) were studied by immunohistochemistry in archival material from 95 renal cell carcinoma patients." (PMID 19552816, 2009).